KLHL2 (kelch like family member 2)
Description:
Substrate-specific adapter of a BCR (BTB-CUL3-RBX1) E3 ubiquitin ligase complex that mediates the ubiquitination of target proteins, such as NPTXR, WNK1, WNK3 and WNK4, leading most often to their proteasomal degradation. The BCR(KLHL2) complex catalyzes ubiquitination and degradation of NPTXR (By similarity). Responsible for degradative ubiquitination of the WNK kinases WNK1, WNK3 and WNK4. Plays a role in the reorganization of the actin cytoskeleton. Promotes growth of cell projections in oligodendrocyte precursors.
Synonyms: MAV; ABP-KELCH; MAYVEN
Tractability: Small molecule: it has a binding pocket of medium quality; it belongs to a druggable protein family. PROTAC: ubiquitination databases record sites on it.
Gene: Protein-coding gene on chromosome 4 (165,207,561 to 165,323,156, forward strand). Ensembl gene ENSG00000109466.
Subcellular location: Cytoplasm, cytoskeleton; Cell projection, ruffle; Cell projection; Cell projection, lamellipodium; Cytoplasm, cytosol
Subcellular location (Human Protein Atlas): Nucleoplasm; Vesicles
Pathways (Reactome):
Immune System: Antigen processing: Ubiquitination & Proteasome degradation
Metabolism of proteins: Neddylation
Gene Ontology:
Molecular function: actin binding; identical protein binding; protein binding; ubiquitin-like ligase-substrate adaptor activity
Biological process: proteasome-mediated ubiquitin-dependent protein catabolic process; protein ubiquitination; protein catabolic process
Cellular component: actin cytoskeleton; Cul3-RING ubiquitin ligase complex; cytoplasm; cytosol; cytoskeleton; lamellipodium; ruffle
Genetic constraint (gnomAD): Loss-of-function variants: 11 observed, 50.62 expected, observed/expected ratio (o/e) 0.22, 90% interval 0.14 to 0.36. The upper end of that interval is the gene's LOEUF score, 0.36, which puts it in group 1 of 6, group 1 being the genes least tolerant of losing a copy. Missense variants: 279 observed, 562.18 expected, observed/expected ratio (o/e) 0.5, 90% interval 0.45 to 0.55. Synonymous variants: 167 observed, 190.66 expected, observed/expected ratio (o/e) 0.88, 90% interval 0.77 to 1.
Homologues: Orthologues: dog KLHL2 (99% identical), pig KLHL2 (99% identical), rabbit KLHL2 (99% identical), mouse Klhl2 (99% identical), rat Klhl2 (99% identical), chimpanzee KLHL2 (99% identical), guinea pig KLHL2 (97% identical), macaque KLHL2 (97% identical), tropical clawed frog klhl2 (86% identical), zebrafish klhl2 (81% identical). Paralogues in human: KLHL3 (77% identical), KLHL17 (48% identical), KLHL20 (44% identical), KLHL12 (40% identical), KLHL5 (40% identical), KLHL1 (39% identical), KLHL4 (38% identical), KEAP1 (37% identical), KLHL8 (36% identical), KLHL18 (36% identical), KLHL28 (35% identical), KLHL24 (34% identical), and 42 more.
Diseases named in the same sentence as KLHL2 in open-access papers:
KLHL2 is named in the same sentence as 11 diseases in open-access papers, as found by Europe PMC text mining. Sharing a sentence is not in itself a finding about the gene and the disease. The quoted sentences say what the papers report.
Hypertension (2 papers, 2014 to 2022). The presence of chronic increased pressure in the systemic arterial system. "KLHL2 has mainly been studied in hypertension, another disease in which PIM kinases play key roles and their overexpression is associated with poor prognosis." (PMID 35326457, 2022). "KLHL2 is best known for its high expression in the brain, whereas KLHL3 may play a dominant role in the kidney, consistent with the effects of KLHL3 mutations in hypertension." (PMID 24641320, 2014).
Alzheimer disease (1 paper, 2024). A progressive, neurodegenerative disease characterized by loss of function and death of nerve cells in several areas of the brain leading to loss of cognitive function such as memory and language. "Among these genes were Klhl2, which has been shown to induce neuronal apoptosis, and Slc38a2, known to be associated with Alzheimer’s disease and modulated by nutritional stress, like amino acid deprivation." (PMID 39456952, 2024).
breast carcinoma (1 paper, 2020). "A previous study indicated that overexpression of KLHL2 promotes breast cancer growth." (PMID 31938050, 2020).
Gordon syndrome (1 paper, 2014). An extremely rare multiple congenital malformation syndrome characterized by congenital contractures of hand and feet with variable degrees of severity of camptodactyly, clubfoot and, less frequently, cleft palate. "Thus far, no mutations in KLHL2 have been described in patients with Gordon's syndrome, but the binding data strongly suggest that KLHL2 will also play a role in regulating WNK isoforms." (PMID 24641320, 2014). "The double glycine motif is conserved in KLHL2 and KLHL3, but there are currently no reported Gordon's syndrome mutations at these sites." (PMID 24641320, 2014).
hematological malignancies (1 paper, 2020). "Little is known about the role of KLHL2 in hematological malignancies." (PMID 31938050, 2020).
tumor (1 paper, 2022). "Previous studies have described the recruitment of USP28 by the E3 ubiquitin ligases kelch-like family member 2 (KLHL2) and ring finger and CHY zinc finger domain containing 1 (RCHY1), but little is known about how these factors are affected by tumor hypoxia." (PMID 35326457, 2022).
KLHL2 also shares sentences with these, for which no sentence is quoted: anaphylaxis (1 paper); colon carcinoma (1); pancreatic cancers (1); psychiatric disorder (1); septic shock (1).